IL13 (interleukin 13)
Diseases named in the same sentence as IL13 in open-access papers (continued):
Sharing a sentence is not in itself a finding about the gene and the disease.
endometriosis (19 papers, 2018 to 2025). The growth of functional endometrial tissue in anatomic sites outside the uterine body. "SOCS1 dysregulation may exacerbate the IL-4 and IL-13 properties associated with endometriosis." (PMID 36120440, 2022). "The association between the gene polymorphism of IL-13 and various infertility risk factors, such as PCOS, endometriosis, premature ovarian failure (POI), and DOR, has been confirmed." (PMID 39996063, 2025). "The TGF-β1 and PDGF-BB produced by Tregs promote lesional growth, EMT, FMT, and fibrosis in endometriosis, while the IL-33 secreted by endometriotic cells transform Tregs into Th2-like Tregs, producing more profibrotic cytokines IL-13, IL-4, and even TGF-β1." (PMID 36428461, 2022). "In particular, M2a macrophages, which can be induced by IL-4 or IL-13—two typical Th2 cytokines—have been reported to be critically involved in fibrogenesis of endometriosis." (PMID 33381124, 2020). "However, some studies showed that patients with endometriosis had much lower levels of IL-13 in their serum and peritoneal fluid compared to the control group." (PMID 39767772, 2024). "At the phyla level, a higher abundance of Proteobacteria in peritoneal fluid could be seen among infertile patients with endometriosis, in which several inflammatory factors, including IL-6, IL-10, IL-13, and TNF-α, may be involved." (PMID 37764164, 2023). "Moreover, the preclinical study has proved its effect of treating endometriosis by significantly reducing rat serum CA-125 levels and IL-18 in peritoneal fluid, and increasing the level of IL-13 in peritoneal fluid." (PMID 35250579, 2022). "IL-4 and IL-13 type I and II receptor signaling pathways are linked to Signal Transducer and Activator of Transcription 6 (STAT6) expression, responsible for mediating IL-4 and IL-13 immune signaling, increase proliferation, adhesion and viability of endometriosis lesions." (PMID 36120440, 2022). "It was reported that the concentration of Th1 cell-related cytokines like interferon-γ (IFN-γ) was lowly expressed, while Th2 cell-related cytokines like interleukins (IL)-4, IL-10, and IL-13 were highly expressed in the serum of the patients with endometriosis." (PMID 34429116, 2021). "IFN-γ, TNF-α, IL-4, and IL-13 are the important cytokines for Th1 and Th2 cells, hence, above results indicated that rhIL-37 maybe improve endometriosis through regulating Th1 and Th2 differentiation." (PMID 34429116, 2021). "Additionally, in the same study, through regression analysis, the combination of SCGF-β, IL-13, and G-CSF concentrations predicted with accuracy the presence of endometriosis (86% sensitivity and 67% specificity)." (PMID 32063886, 2019). "Besides, the levels of serum IL-4 and IL-13 were upregulated in the mice with endometriosis, but rhIL-37 treatment could effectively decline the levels of them." (PMID 34429116, 2021). "One study evaluated how IL-4 and IL-13 increase the expression of periostin and TCF21, which are involved in the regulation of fibrosis in endometriosis." (PMID 38337827, 2024). "After the analysis, it was detected that the levels of IL-6, IL-10, IL-13, and TNF-α were significantly higher in women with endometriosis and infertility (P < 0.05)." (PMID 38601772, 2023). "They found that IL-6, IL-10, IL-13, and TNF-α are highly expressed in the peritoneal fluid of endometriosis patients." (PMID 33354460, 2020). "Extracts of S. miltiorrhiza have also shown promise in treating endometriosis by markedly reducing the serum levels of CA125 and the levels of IL-18 and TNF-α, by significantly increasing the levels of IL-13 in the peritoneal fluid in a rat model." (PMID 30402122, 2018). "Thus, these inflammatory factors (IL-6, IL-10, IL-13, and TNF-α) can be used as essential reference indexes for endometriosis diagnosis complicated with infertility." (PMID 33354460, 2020).
endometriosis (continued). "Recently, significantly higher concentrations of SCGF-β, IL-8, HGF, and MCP-1 have been reported, as well as lower levels of anti-inflammatory cytokine IL-13 in endometriosis patients such as those found in women without endometriosis." (PMID 32063886, 2019). "However, PBS-Treated Mice also showed decreased plasma levels of Eotaxin, IL-9, IL-13, and MIP-1α, suggesting that the difference may stem from the induction endometriosis, and not from the IL-17A injection." (PMID 32117261, 2020).
nematode infection (19 papers, 2009 to 2025). "The increased expression of IL-13 in the jejunum and caeca during the early stage of mixed nematode infection (A. galli and H. gallinarum) has been associated with robust worm expulsion and the absence of parasite eggs." (PMID 39342330, 2024). "We observed positive associations between Sm infection and PPD-specific IL-13, and IgG4 in the urban survey, and between nematode infection and PPD-specific IgG in the rural survey." (PMID 32387542, 2020). "Since immunity to the related gastrointestinal nematode parasite N. brasiliensis is also highly dependent on IL-4R/Stat6/IL-13-dependent signaling, we examined whether resistance to nematode infection in the small intestine was affected by Retnla deficiency." (PMID 19381262, 2009). "The production of IL-4 and IL-13 during nematode infection in vivo is mainly initiated by the alarmins IL-25, IL-33 and TSLP released by epithelial and stromal cells." (PMID 38414039, 2024). "In response to nematode infection, mast cells also produce Th2-type cytokines such as IL-13, IL-4, and IL-5, which contribute to the recruitment of inflammatory cells such as eosinophils, natural killer (NK) cells, and neutrophils to the mucosal sites." (PMID 38338687, 2024). "IL-13 is key to resistance to multiple GI nematode infections and ILC2 are a potent source of this cytokine with these cells sufficient for resistance to N. brasiliensis infection." (PMID 31730667, 2019). "Nematode infection induces polarized type 2 immunity characterized by increased expression of cytokines such as IL-4, IL-5, IL-13, and IL-25." (PMID 26377648, 2015). "Host defense against nematode infection relies on Th2 cytokines IL-4 and IL-13 activating STAT6 signaling pathways, which then leads to up-regulation of various downstream effector molecules as well as stereotypic alterations in gut function." (PMID 26377648, 2015). "In contrast, up-regulation of the Th2 cytokines, IL-4 and IL-13, during nematode infection and allergy leads to development of alternatively activated macrophages (M2) that are important for tissue repair." (PMID 24465430, 2014). "The host response to nematode infection is characterized by induction of a T-helper 2 (Th2) immune response, involving the elevated production of inteleukin-4 (IL-4), IL-5, IL-10 and IL-13." (PMID 24465430, 2014). "Among the identified downstream effector molecules of IL-25, IL-13 is critical for the promotion of type 2 immunity important for clearance of parasitic nematode infections and for the characteristic changes in gut function after nematode infection." (PMID 25937893, 2014). "RELM-β is increased significantly by nematode infection and is necessary for IL-4/IL-13-dependent expulsion of enteric nematodes." (PMID 24465430, 2014). "It is known that IL-13 activation of STAT6 during nematode infection increases the expression of IL-13Rα2, 5-HT2A, and arginase I in WT." (PMID 23536877, 2013). "Recently, we described that nematode infection induced an IL-4/IL-13-driven intestinal smooth muscle hypercontractility, which was absent in global IL-4Rα−/− mice and reduced in smooth muscle cell-specific IL-4Rα−/− mice." (PMID 23284939, 2012). "On the other hand, Th2 cells play a central role in mediating the protective immunity against parasitic nematode infections by releasing an array of cytokines, such as IL-4 and IL-13." (PMID 21414188, 2011). "In addition, IL-13 and IL-4 increase smooth muscle contractility in the gut during nematode infections." (PMID 38338687, 2024). "Interestingly, the production of IL-25 following nematode infection is itself dependent on IL-4Rα, mediated by IL-13 activation of STAT6." (PMID 30238872, 2018). "In addition to underpinning the role of interleukin-13 (IL-13)-mediated protective immunity to gastrointestinal-dwelling nematode infections, the naturally rodent-infecting species, Trichuris muris, has been successfully used as an experimental model of chronic STH helminth infection." (PMID 31138806, 2019).
nematode infection (continued). "Following nematode infection, Tuft cells in the intestinal epithelium secrete IL-25; this activates ILC2 which secrete IL-4 and IL-13." (PMID 40565065, 2025). "TFF3 is IL-4/IL-13-regulated and interacts with the mucin MUC2 (not on array) to alter mucus viscosity, with which it co-localises in human intestinal goblet cells, and up-regulation of both these mucus components has been associated with responses to nematode infection in mice." (PMID 21682880, 2011).
tuberculosis (19 papers, 2012 to 2025). A chronic, recurrent infection caused by the bacterium Mycobacterium tuberculosis. "IL-13-over-expressing mice are associated with more necrosis in granuloma and getting more similarity with post primary tuberculosis." (PMID 31363402, 2019). "Abundance of IL13 has predicted progression to active tuberculosis disease in high-risk groups, suggesting higher susceptibility as well as a lower ability to mount adequate immune response to recover from disease in our Maf-infected patients." (PMID 27192147, 2016). "What is interesting about this last finding is that overexpression of IL-13 has been linked to increased tuberculosis susceptibility in a B6 mice model, while, in humans, some polymorphisms of IL-13 genes have been associated also with increased susceptibility to the disease." (PMID 36678397, 2022). "In murine Mtb infection studies IL13 was associated with tuberculosis associated pathology; overexpressing IL13 resulted in enhanced pathology mimicking human TB lesions." (PMID 26137541, 2015). "Th2 cytokines, i.e., IL-4, IL-6, IL-10, IL-13, etc., inhibit Th1 responses and thus cross-regulate and influence the progression to active tuberculosis." (PMID 36776550, 2022). "IL-10 and IL-13 are two cytokines that undergo changes in the course of tuberculosis and can be raised in pathogenesis of lung dysfunction." (PMID 31363402, 2019). "The best fit model found was log(P(Tuberculosis)/P(sarcoidosis)) = 1.214 + 8.884 * IL1 + 0.075 * IFN + 0.32 * IL12p70 + 0.039 * TNF − 0.097 * IL5 − 0.015 * IL8 − 0.73 * IL13 − 0.606 * IL10 − 2.404 * IL2 − 4.231 * IL4." (PMID 22815689, 2012). "Median BAL levels of the Th2 cytokines IL-4 and IL-13 were significantly higher in sarcoidosis and tuberculosis compared to healthy BALs (p < 0.001)." (PMID 22815689, 2012). "With regards to tuberculosis, we are unaware of previous work investigating IL-13 BAL levels but increased IL-4 secretion from both CD4+ and CD8+ T-cells in active pulmonary tuberculosis has been shown compared to those with latent infection." (PMID 22815689, 2012). "tuberculosis coinfections in Indian adults are associated with lower circulating levels of inflammatory cytokines, including IFN-γ, TNF-α, IL-17A, and IL-17F alongside increased type 2 cytokines IL-4, IL-5, and IL-13." (PMID 39816832, 2023). "Besides tuberculosis, mb-1creIL-4Rα-/lox mice during N. brasiliensis infection uncovered that IL-4Rα-responsive B cells-driven IL-13 and antigen processing contribute to T cell-mediated protective immunity." (PMID 34220793, 2021). "M. tuberculosis-infected interleukin-13-overexpressing (IL-13tg) mice develop a TB pathology very similar to patients and, in contrast to other mouse models, also share pathogenetic mechanisms." (PMID 34871095, 2022). "Therefore, it might be interesting to address the impact of ACC1 deletion in macrophages on the outcome of anti-mycobacterial immunity and Mtb survival in other models, such as in the post-primary tuberculosis model or in IL-13-overexpressing mice, where “foamy” macrophages are highly abundant." (PMID 29675017, 2018). "Tuberculosis triggers a type 1 immune response characterized by IL-12, IFN-γ, and TNF-α production, while toxocariasis elicits a type 2 response, mediated by cytokines such as IL-4, IL-5, IL-13, and IL-33." (PMID 40943043, 2025). "Changes in IL-13 were not significant during tuberculosis treatment in patients with normal, restrictive or obstructive spirometry in our study." (PMID 31363402, 2019). "Despite claimed role of IL-13 in pathogenesis of tuberculosis, its relationship with respiratory dysfunction is not clear." (PMID 31363402, 2019). "There is not much information about the role of interleukin 13 in patients with tuberculosis and also post tuberculosis complications." (PMID 31363402, 2019).
gastric cancer (17 papers, 2014 to 2025). A primary or metastatic malignant neoplasm involving the stomach. "Regulatory T (Treg) cells expressing the Foxp3 transcription factor play a critical role in promoting the stemness of gastric cancer cells through the IL13/STAT3 pathway and also help in reducing overactive immune responses within the tumor microenvironment." (PMID 39605357, 2024). "In fact, a mixed Th1/Th2 immune response is associated with non-atrophic chronic gastritis, while a prevalent Th2 immune response, mostly IL-13-mediated, characterizes patients with intestinal metaplasia and intestinal-type gastric cancer." (PMID 38339273, 2024). "Another recent study identified TNF+ Tregs as a source of IL-13 and proposes that IL-13 promotes self-renewal, migration and colony formation of gastric cancer cells via the phosphorylation of STAT3." (PMID 38339273, 2024). "Our study shows that TNF+ Tregs affect the stemness of gastric cancer cells through IL-13 secretion." (PMID 37534250, 2023). "Stattic abrogated the self-renewal, migration and colony formation of gastric cancer cells induced by IL-13." (PMID 37534250, 2023). "Our studies have further demonstrated that TNF+ Tregs promote the stemness of gastric cancer cells through the IL13/STAT3 pathway." (PMID 37534250, 2023). "In this paper, we investigated the promotion effects of TNF+ Tregs on stemness in gastric cancer cells through the IL13/STAT3 signaling pathway." (PMID 37534250, 2023). "We found that TNF+ Tregs released a high level of the anti-inflammatory cytokine IL13, which promotes the malignant biological function of gastric cancer cells by activating STAT3." (PMID 37534250, 2023). "After binding to its receptor, IL-4 and IL-13 can mediate tumor cell proliferation, survival, and metastasis in colorectal and gastric cancers." (PMID 35432477, 2022). "This suggests that the effect of TNF+ Tregs on gastric cancer cells is dependent on IL13." (PMID 37534250, 2023). "We next examined the molecular mechanisms by which IL13 promotes gastric cancer stemness." (PMID 37534250, 2023). "However, elevated MDSCs are associated with a significant elevation in Th2 cytokine, interleukin-13 (IL-13), and disease prognosis in lung, oesophageal, pancreatic, and gastric cancers." (PMID 32973748, 2020). "In the collinearity analysis, we annotated the function of the coexpression gene network module and compared the gene association changes of the subnetwork modules including interleukin-4 and interleukin-13 signaling pathway in normal samples and gastric cancer samples." (PMID 32832545, 2020). "In addition, Th-2 cells also secret IL-13, the predominant source of IL-13 in gastric cancer remains to be verified." (PMID 27351230, 2016). "As a result, we raised hypothesis that mast cells can secret IL-13 to promote metastasis via IL-13Rα2 in gastric cancer." (PMID 27351230, 2016). "Recent studies involving single-cell RNA sequencing of gastric cancer and adjacent tissues found that Tregs were recruited to gastric cancer tissues and have further demonstrated that Tregs promote the stemness of gastric cancer cells through the IL13/STAT3 pathway." (PMID 39605357, 2024). "Here the authors show that tuft cells and ILC2s are increased during gastric cancer development and that the pharmacologic inhibition of tuft cell derived IL25 or ILC2-produced IL13 reduces gastric tumor growth." (PMID 37898600, 2023). "In the light of existing controversies, the aim of present study is a comprehensive comparative analysis of IL-4 and IL-13 expression at mRNA and protein level, local and systemic, in CRC as compared to esophageal and gastric cancers." (PMID 32512917, 2020). "To understand the relationship of RORα and ILC2s-related markers and signature cytokines in patients with gastric cancer, we analyzed the correlation between RORα and T1/ST2, IL-17RB, CRTH2, ICOS, CD45, IL-13, and IL-5 in mRNA levels." (PMID 24741632, 2014).
gastric cancer (continued). "For downstream inflammatory factors, our findings were supported by previous studies that demonstrated a strong association between pre-neoplastic alterations and the development of gastric cancer, involving various inflammatory regulators including bNGF, GCSF, IL-13, IL-5, IL-7, and MCSF." (PMID 39439893, 2024). "The correlation between the mRNA levels of IL-13 and ICOS and CD45 was analyzed, respectively, and the results demonstrated that there was a positive correlation between IL-13 and ICOS and CD45 in patients with gastric cancer." (PMID 24741632, 2014). "Furthermore, there was a positive correlation between IL-13 and ICOS and CD45 in gastric cancer." (PMID 24741632, 2014).